SLC41A1 (solute carrier family 41 member 1)
Description:
Na(+)/Mg(2+) ion exchanger that acts as a predominant Mg(2+) efflux system at the plasma membrane. Transporter activity is driven by the inwardly directed electrochemical gradient for Na(+) ions, thus directly depends on the extracellular Na(+) ion concentration set by Na(+)/K(+) pump. Generates circadian cellular Mg(2+) fluxes that feed back to regulate clock-controlled gene expression and metabolism and facilitate higher energetic demands during the day. Has a role in regulating the activity of ATP-dependent enzymes, including those operating in Krebs cycle and the electron transport chain (By similarity).
Synonyms: MgtE; NPHPL2
Tractability: Antibody: UniProt places it where antibodies can reach, with high confidence; its Gene Ontology location is reachable by antibodies, with high confidence; UniProt predicts a signal peptide or a membrane-spanning region. PROTAC: ubiquitination databases record sites on it.
Gene: Protein-coding gene on chromosome 1 (205,789,091 to 205,813,755, reverse strand). Ensembl gene ENSG00000133065.
Subcellular location: Cell membrane; Basolateral cell membrane
Subcellular location (Human Protein Atlas): Mitochondria
Pathways (Reactome):
Transport of small molecules: Metal ion SLC transporters
Gene Ontology:
Molecular function: magnesium ion transmembrane transporter activity; magnesium:sodium antiporter activity; protein binding; transmembrane transporter activity; monoatomic cation transmembrane transporter activity
Biological process: cellular response to magnesium ion; intracellular magnesium ion homeostasis; magnesium ion transmembrane transport; magnesium ion transport; metal ion transport; monoatomic cation transport; sodium ion transmembrane transport
Cellular component: basolateral plasma membrane; plasma membrane; protein-containing complex
Genetic constraint (gnomAD): Loss-of-function variants: 20 observed, 49.5 expected, observed/expected ratio (o/e) 0.4, 90% interval 0.28 to 0.59. The upper end of that interval is the gene's LOEUF score, 0.59, which puts it in group 2 of 6, group 1 being the genes least tolerant of losing a copy. Missense variants: 504 observed, 710.57 expected, observed/expected ratio (o/e) 0.71, 90% interval 0.66 to 0.76. Synonymous variants: 282 observed, 287.96 expected, observed/expected ratio (o/e) 0.98, 90% interval 0.89 to 1.08.
Gene-disease validity (ClinGen):
ClinGen rates the evidence that SLC41A1 causes each of these diseases.
kidney disorder (autosomal recessive): Limited. A disease involving the kidney.
Homologues: Orthologues: chimpanzee SLC41A1 (100% identical), macaque SLC41A1 (100% identical), dog SLC41A1 (98% identical), guinea pig SLC41A1 (98% identical), pig SLC41A1 (98% identical), rat Slc41a1 (98% identical), mouse Slc41a1 (98% identical), rabbit SLC41A1 (91% identical), tropical clawed frog slc41a1 (77% identical), zebrafish slc41a1 (76% identical), Caenorhabditis elegans K07H8.2 (44% identical), Drosophila melanogaster CG33181 (41% identical), and 2 more. Paralogues in human: SLC41A2 (60% identical), SLC41A3 (48% identical).
Diseases named in the same sentence as SLC41A1 in open-access papers:
SLC41A1 is named in the same sentence as 30 diseases in open-access papers, as found by Europe PMC text mining. Sharing a sentence is not in itself a finding about the gene and the disease. The quoted sentences say what the papers report.
Parkinson disease (8 papers, 2013 to 2025). A progressive degenerative disorder of the central nervous system characterized by loss of dopamine producing neurons in the substantia nigra and the presence of Lewy bodies in the substantia nigra and locus coeruleus. "SLC41A1 (A1) SNPs rs11240569 and rs823156 are associated with altered risk for Parkinson’s disease (PD), predominantly in Asian populations, and rs708727 has been linked to Alzheimer’s disease (AD)." (PMID 35163527, 2022). "For example, in patients with Parkinson’s disease from China, Taiwan, and Iran, the SLC41A1 gene was found to have different variants, which might be associated with its reduced expression and loss of function." (PMID 31076559, 2019). "Variations in the SLC41A1 gene within the PARK16 locus in Parkinson’s disease patients have a significant impact on the pathogenesis of Parkinson’s disease as well as on ion homeostasis and the function of dopamine neurons." (PMID 39200180, 2024). "The human orthologs of MgtE, the SLC41 proteins (SLC41A1, SLC41A2, and SLC41A3), also transport Mg2+ ions, and mutations in these proteins are associated with type 2 diabetes, Parkinson disease, and nephronophthisis." (PMID 33905418, 2021). "Also, the SLC41A1 variant might predict the risk of Parkinson’s disease in the Chinese population." (PMID 31076559, 2019). "The function of SLC41A1 was recently studied in neurodegeneration such as Parkinson’s diseases; however, its role in cancer, especially PDAC, was yet to be identified." (PMID 31076559, 2019).
nephronophthisis (5 papers, 2019 to 2024). Progressive tubulointerstitial injury, inherited in an autosomal recessive pattern, caused by mutations in genes involved in ciliary function, which may result in an end stage renal failure. "Mutations in SLC41A1 were also observed in nephronophthisis, which resulted in the in-frame deletion of a transmembrane helix." (PMID 31076559, 2019). "An exon-skipping SLC41A1 mutation has been previously associated with a nephronophthisis-like phenotype." (PMID 30417250, 2019). "G233 in human SLC41A1, involved in NPHPL2 (nephronophthisis-like nephropathy, an autosomal recessive early onset renal insufficiency), was conserved in all salmon Slc41 family members, and more largely in all the proteins in the dataset." (PMID 39614204, 2024). "Mutated SLC41A1 was not able to maintain renal Mg2+ homeostasis, resulting in tubular defects and nephronophthisis-like phenotypes." (PMID 31076559, 2019).
pancreatic ductal adenocarcinoma (4 papers, 2019 to 2024). An infiltrating adenocarcinoma that arises from the epithelial cells of the pancreas. "The aim of this study was to identify the function of the Mg2+ transporter protein solute carrier family 41 member 1 SLC41A1 in pancreatic ductal adenocarcinoma and the underlying mechanisms." (PMID 31076559, 2019). "SLC41A1 expression is correlated with clinical outcomes in patients with pancreatic ductal adenocarcinoma, with SLC41A1 being downregulated in tumors." (PMID 33450887, 2021). "Furthermore, SLC41A1 was reported to be downregulated in human pancreatic ductal adenocarcinoma, and SLC41A1 overexpression inhibited cell proliferation and invasion, and suppressed orthotopic tumour growth in a mouse model." (PMID 39628683, 2024). "The results of this study suggest that SLC41A1 may be a potential target for the treatment of pancreatic ductal adenocarcinoma." (PMID 31076559, 2019). "However, the roles of SLC41A1 in HCC was opposite to those in human pancreatic ductal adenocarcinoma, where SLC41A1 was downregulated and inhibited proliferation, migration and invasion through magnesium-dependent Akt/mTOR inhibition and bax-regulated apoptosis." (PMID 39628683, 2024).
Hypomagnesemia (3 papers, 2019 to 2024). An abnormally decreased magnesium concentration in the blood. "Based on the SLC41A1 function disclosed, patients with hereditary hypomagnesemia should be screened for SLC41A1 mutations." (PMID 30417250, 2019). "SLC41A1 hasbeen extensively studied in vitro and in vivo.However, SLC41A1 KO mice have normal serum Mg2+ levels.SLC41A3 on the other hand, is highly expressed in the DCT and invivo knockout models show a hypomagnesemia phenotype." (PMID 38871680, 2024). "Under hypomagnesemia, low serum (i.e., extracellular) Mg levels can activate Mg transporters such as TRPM7 and SLC41A1 to induce Mg efflux from cells to increase serum Mg levels." (PMID 32977544, 2020). "Mechanisms for hypomagnesemia include increased intestinal mRNA expression of TRPM6, TRPM7, and SLC41A1 and therefore increased Mg extrusion." (PMID 32977544, 2020).
breast carcinoma (2 papers, 2018 to 2024). "Similarly, SLC41A1 expression was increased in breast cancer, and knockdown of SLC41A1 decreased cell viability in breast cancer cells." (PMID 39628683, 2024).
diabetes (2 papers, 2019 to 2024). "SLC41A1 expression gradually decreased with the developing stages of PDAC and was inversely associated with the presence of diabetes mellitus, one of the significant risk factors for PDAC." (PMID 31076559, 2019).
pancreatic cancer (2 papers, 2019 to 2020). "In pancreatic cancer cells, overexpression of SLC41A1, a membrane protein for Mg2+ extrusion, and the resulting low [Mg2+]i, inhibited the Akt/mTOR pathway and cancer proliferation." (PMID 32927908, 2020). "The overexpression of SLC41A1 in KP3 cells reduced the growth rate of pancreatic tumours, as evidenced by the smaller increase in luciferase signal." (PMID 31076559, 2019). "To further understand the role of SLC41A1 as a tumour suppressor in PDAC, we used a non-viral plasmid encoding the ORF of SLC41A1 to overexpress the SLC41A1 protein in parallel with the Panc-1 pancreatic tumour cell line." (PMID 31076559, 2019). "At the end of the experiment, we dissected the pancreatic tumours from the mice and found that the pancreatic tumour size was significantly reduced in those injected with KP3/SLC41A1 cells." (PMID 31076559, 2019).
chronic kidney disease (1 paper, 2023). Impairment of the renal function secondary to chronic kidney damage persisting for three or more months. "SLC41A1 was essential for magnesium homeostasis in vivo and had a Mendelian association with nephronophthisis-like nephropathy-2 (OMIM phenotype number, #619468) that is the most common genetic cause of chronic kidney disease in early life." (PMID 37980427, 2023).
head and neck cancer (1 paper, 2019). A primary or metastatic malignant neoplasm affecting the head and neck. "Interestingly, a recent analysis in patients with head and neck cancer undergoing cisplatin chemotherapy showed that SLC41A1 level was correlated with serum levels of Mg2+, suggesting that SLC41A1 might undergo Mg2+ extrusion from tumour tissues." (PMID 31076559, 2019).
hydronephrosis (1 paper, 2016). Collection of urine in the renal pelvis that results in dilatation of the renal pelvis and calyces. "More patients with mutations in SLC41A1 should be identified and examined for hydronephrosis to allow final conclusions on the kidney phenotype of these patients." (PMID 27349617, 2016). "Moreover, in contrast to the NPHP-like phenotype in patients with SLC41A1 mutations, the kidney size was markedly increased in the Slc41a3−/− mice that suffered from hydronephrosis." (PMID 27349617, 2016).
Kidney Cyst (1 paper, 2024). Abnormal fluid filled sac within the kidney, either acquired or congenital. "slc41a1 knock-down in zebrafish also results in kidney cysts." (PMID 39614204, 2024).
kidney failure (1 paper, 2019). An acute or chronic condition that is characterized by the inability of the kidneys to adequately filter the blood. "However, it must be indicated that kidney failure typically results in Mg2+ conservation, an effect that may mask renal Mg2+ reabsorption defects in these specific SLC41A1 patients." (PMID 30417250, 2019).
osteoporosis (1 paper, 2017). A condition of reduced bone mass, with decreased cortical thickness and a decrease in the number and size of the trabeculae of cancellous bone (but normal chemical composition), resulting in increased fracture incidence. "Tissue-specific SLC41A1 could be a potential treatment for bone mass loss; in addition, caution should be taken regarding the role of magnesium in osteoporosis and the design of magnesium alloys for implantation." (PMID 28222767, 2017). "Together, tissue-specific SLC41A1 could be a potential treatment for bone mass loss; in addition, caution should be taken regarding the role of magnesium in osteoporosis and the design of magnesium alloys for implantation because local high magnesium concentration could generate from fast degrading." (PMID 28222767, 2017).
preeclampsia (1 paper, 2019). Preeclampsia is a hypertensive disorder of pregnancy that is characterized by new-onset hypertension with proteinuria presenting after 20 weeks of gestation, and depending on mild or severe forms may initially present with severe headache, visual disturbances, and hyperreflexia. "SLC41A1 is overexpressed in the placenta of preeclamptic women and is responsible for changes in Mg2+ homeostasis in the development of preeclampsia." (PMID 31076559, 2019).
tumor (6 papers, 2019 to 2024). "SLC41A1 expression is inversely correlated with tumor grade and was positively associated with a better outcome for patients." (PMID 33450887, 2021). "We observed that the tumour-suppressive activity of SLC41A1 appeared to be associated with its function as an Mg2+ transporter." (PMID 31076559, 2019). "Clinically, aberrant expression of SLC41A1 were correlated with clinicopathological characteristics, demonstrating that high SLC41A1 expression was positively associated with several unfavorable factors, such as tumor status, residual tumor and histologic grade." (PMID 39628683, 2024). "Compared to the non-tumor tissues, SLC41A1 expression was elevated in both unpaired HCC samples (1.5156±0.3675 vs 2.5438±1.1555) and paired HCC tissues (1.5156±0.3675 vs 2.5586±1.08)." (PMID 39628683, 2024). "Cellular experiments showed that knockdown of SLC41A1 inhibited proliferation, migration and invasion of HCC, whereas SLC41A1 overexpression exerted the tumor-promoting effects." (PMID 39628683, 2024). "By GSEA, we further found that SLC41A1 was positively correlated with several tumor progression-related pathways, including degradation of ECM, ECM organization, O-linked glycosylation, collagen formation, collagen degradation and assembly of collagen fibrils." (PMID 39628683, 2024). "By immunostaining of HCC, non-tumor and normal liver sections, we confirmed the upregulation of SLC41A1 in HCC tissues compared to non-tumor and normal livers." (PMID 39628683, 2024). "By immunostaining, we verified that expression of SLC41A1 was dramatically upregulated in HCC tissues than in non-tumor tissues and normal liver tissues, which made our results more convincing." (PMID 39628683, 2024). "We found that, compared with non-tumor samples, SLC41A1 was upregulated in HCC samples in GSE25097 (0.8817±0.3109 vs 1.5190±0.9653) and GSE76427 (123.0956±23.8637 vs 168.8677±62.4464)." (PMID 39628683, 2024). "An increase in AKT activity and supplementation with Mg2+ abolished SLC41A1-induced tumor suppression." (PMID 33450887, 2021). "Overexpression of SLC41A1 suppressed orthotopic tumor growth in a mouse model and reduced the cell proliferation, colony formation, and invasiveness of KP3 and Panc-1 cell lines." (PMID 33450887, 2021). "Suppressed protein and mRNA expression of SLC41A1 was validated in six pairs of human PDACs and adjacent non-tumour tissues." (PMID 31076559, 2019). "Three of these proteins were correlated with clinical outcomes in patients, among which SLC41A1 was downregulated in tumour." (PMID 31076559, 2019). "This inactivation was correlated with the tumour-suppressive function of SLC41A1, as evidenced by the observation that recovery of Akt activity with SC79 (10 μg/mL) markedly abrogated the inhibition of PDAC cell proliferation by SLC41A1 overexpression." (PMID 31076559, 2019). "An increase in Akt activity and supplementation with Mg2+ abolished SLC41A1-induced tumour suppression." (PMID 31076559, 2019). "We found that SLC41A1 was correlated with gender, tumor status, residual tumor, histologic grade." (PMID 39628683, 2024). "In vitro and in vivo studies verified the function of SLC41A1 as a tumour suppressor." (PMID 31076559, 2019). "This led to partial abrogation of the anti-tumour effects of SLC41A1 overexpression in PDAC." (PMID 31076559, 2019). "Suppression of Bax abrogated the tumour-suppressive effects of SLC41A1." (PMID 31076559, 2019). "Furthermore, silencing of Bax protein by RNA interference reduced the tumour-suppressive effects of SLC41A1, suggesting that Bax activation of the intrinsic apoptotic pathway mediates the tumour-suppressive effects of SLC41A1." (PMID 31076559, 2019). "We found that SLC41A1 has tumour-suppressive functions in PDAC." (PMID 31076559, 2019). "The findings from our study support the tumour-suppressive role of SLC41A1 in PDAC." (PMID 31076559, 2019).
tumor (continued). "Overexpression of SLC41A1 suppressed orthotopic tumour growth in a mouse model and reduced the cell proliferation, colony formation, and invasiveness of KP3 and Panc-1 cells, which may have been associated with the increased population of apoptotic-prone cells." (PMID 31076559, 2019). "Overexpression of SLC41A1 reduced tumour growth in an orthotopic mouse model of PDAC and decreased the in vitro proliferation of PDAC cells, which might be due to a reduction in the MMP, and subsequent release of Cytochrome C to trigger caspase-dependent apoptosis." (PMID 31076559, 2019). "Data from TCGA and GEO database consistently showed that SLC41A1 was upregulated in HCC tissues, compared to non-tumor tissues." (PMID 39628683, 2024). "In this study, we found that SLC41A1 overexpression in PDAC cells inhibited the in vitro proliferation and in vivo tumour growth, as a result of the apoptotic-like phenotype of SLC41A1-overexpressing cells." (PMID 31076559, 2019). "To determine whether the tumour-suppressive effects of SLC41A1 were associated with its function as an Mg2+ transporter, we evaluated the activity of Akt/mTOR in SLC41A1-overexpressing PDAC cells and found that the overexpression of SLC41A1 significantly inhibited Akt/mTOR activity." (PMID 31076559, 2019). "We found that SLC41A1 was downregulated in PDAC and had tumour-suppressive effects." (PMID 31076559, 2019). "Cellular Mg2+ transporters SLC41A1 and CNNM4 function as Na+/Mg2+ exchangers, suggesting that Na may be reduced in tumor samples since Mg was elevated, and our results confirmed this possibility." (PMID 31643147, 2019). "Nevertheless, there was no obvious alteration of SLC41A1 and SLC41A2 expression existing in neoplasm tissues and normal tissues." (PMID 34819993, 2021).
cancer (5 papers, 2018 to 2025). A tumor composed of atypical neoplastic, often pleomorphic cells that invade other tissues. "mRNA expression of MHG was positively correlated with CNV in most cancers, such as SLC41A1, CNNM2, and TRPM7 in SKCM, LUAD, SARC, BRCA, LUSC and OV (P < 0.05)." (PMID 41174507, 2025). "SLC6A14 was recently identified as a novel druggable target in PDAC, suggesting the validity of our screening results, whereas the role of SLC41A1 has rarely been studied in cancer." (PMID 31076559, 2019). "The role of SLC41A1 in cancer has not yet been systematically evaluated." (PMID 31076559, 2019).
SLC41A1 also shares sentences with these, for which no sentence is quoted: Alzheimer disease (2 papers); depression (2); renal failure (2); alcohol dependence (1); ciliopathies (1); cognitive disorder (1); colon cancer (1); epilepsy (1); infection (1); nephronophthisis-like nephropathy 2 (1); neurodegenerative disease (1); Obesity (1); Renal cyst (1); type 2 diabetes (1).